CD4 (CD4 molecule)
Diseases named in the same sentence as CD4 in open-access papers (continued):
Sharing a sentence is not in itself a finding about the gene and the disease.
HIV-1 infection (continued). "In summary, our results demonstrated that CXCR4 disruption in CD4+ T cell lines using lentiviral vectors expressing SaCas9/sgRNAs results in resistance to HIV-1 infection." (PMID 29141633, 2017). "In this regard, previous studies reported that HIV-1 infection induces the activation of CD4+ T cells of infected individuals." (PMID 28475648, 2017). "Consistent with our previous findings, HIV-1 infection led to the severe depletion of activated CD4+ T cells in humanized mice." (PMID 28475648, 2017). "These cells are less permissive to HIV-1 infection compared to activated CD4+ T-cells, which is mainly due to host restriction factors that serve an immediate role in controlling the establishment or spread of viral infection." (PMID 29176984, 2017). "He presented 2 years earlier with pulmonary tuberculosis and HIV-1 infection with nadir CD4 count 50 cells/mm3 and viral load >100,000 copies/ml." (PMID 28344518, 2017). "Here we demonstrated that HIV-1 infection induces immune activation in humanized mice, as observed in infected individuals, and augments the expression of endogenous A3H in the human CD4+ T cells of infected mice." (PMID 28475648, 2017). "Our group also reported that disruption of the CXCR4 co-receptor by CRISPR-Cas9 resulted in protection of primary CD4+ T cells from HIV-1 infection." (PMID 28904745, 2017). "Remarkably, silencing HIF-1α expression in CD4+ T cells reverted the promotion of cell death and production of proinflammatory cytokines induced by HIV-1 infection." (PMID 28953320, 2017). "On the one hand, two studies report that productive HIV-1 infection of CD4+ T cells (primary cells or MOLT-X4 cell line) downregulates the autophagy pathway." (PMID 28946621, 2017). "Primary HIV-1 infection invariably leads to life-long chronic infection characterized by viral replication, plasma viremia, and the slow decline of CD4+ T cell numbers." (PMID 28553284, 2017). "A potential strategy to cure HIV-1 infection is to use latency reversing agents (LRAs) to eliminate latent reservoirs established in resting CD4+ T (rCD4+) cells." (PMID 28539614, 2017). "Research efforts directed at eliminating reservoirs of HIV-1 infection have focused on latently infected CD4+ T cell subsets." (PMID 28279181, 2017). "Altogether, these findings suggest that the immune activation triggered by HIV-1 infection augments A3H expression in CD4+ T cells of infected humanized mice." (PMID 28475648, 2017). "Herbeuval and colleagues have shown that IFNR blockade results in decreased TRAIL/DR5-mediated apoptosis and caspase-3 activity in CD4 T-cells using an in vitro HIV-1 infection model." (PMID 29301196, 2017). "Immune activation induced by HIV-1 infection provides more CD4+ T cell targets for viral replication, increases T cell turnover and depletion, and eventually initiates a vicious cycle of uncontrolled viral replication." (PMID 28839349, 2017). "The ubiquitin ligase Peli1 encoded by PELI1 inversely regulated T lymphocyte activation, whose expression level was decreased in our study, partly indicating hyperactivation of CD4+ T cells related to pathogenesis in HIV-1 infection." (PMID 28222782, 2017). "Two other mutants, Q94A and K142A, which are variable residues in CD4 of primate animals and are proximal to this interface, were chosen to test the specificity of this interface in HIV-1 infection." (PMID 28429756, 2017). "By acting on CD4, these microRNAs control the susceptibility of differentiated THP-1 cells to HIV-1 infection." (PMID 29301198, 2017). "Th1/17 CD4+ T cells have a role as a long-term reservoir for HIV-1 infection, and are unaffected by cART." (PMID 28060843, 2017). "It is a potent inhibitor of HIV-1 infection in CD4+ T cells and macrophages, as well as monocyte-derived immature dendritic cells (iDCs)." (PMID 28452924, 2017). "The high on-target ratio in TZM-bl, Jurkat T cells, and human CD4+ T cells were shown to protect cells from X4- or/and R5-tropic HIV-1 infection." (PMID 28904745, 2017).
HIV-1 infection (continued). "Using the LPAC model, we previously showed that exposure of LPMCs to gut microbes enriched in the intestinal mucosa of HIV-1-infected patients enhanced HIV-1 infection and CD4+ T cell death." (PMID 28241075, 2017). "We also recognized that there were a few differences between two series including the duration of infection, the definitions of disease stages of HIV-1 infection and chronic progression, viral load and CD4+ T cell counts." (PMID 28222782, 2017). "Analysis of HIV-1 infection of CD4+ T lymphocytes showed that transfection of Hrs and rabankyrin-5 siRNAs reduced the spread of both X4-tropic HIV-192UG029 and R5-tropic HIV-1SF170 viruses from tonsil epithelial cells to CD4+ T lymphocytes by ~55–60%." (PMID 28241053, 2017). "Massive depletion of CD4+ T cells in lymphoid tissue, most profoundly in gut-associated lymphoid tissue (GALT), in the first weeks of HIV-1 infection sets the overall course of the ensuing disease." (PMID 28125732, 2017). "We conclude that CXCL14 was unable to synergize with CXCL12 in the inhibition of HIV-1 infection, but, instead, substantially enhanced the infection of CD4+ target cells with both X4 and R5 HIV-1 particles." (PMID 28360196, 2017). "CD4+ T cells are the major targets of HIV-1 infection, and their preferential depletion during the course of infection is the hallmark feature of progression to AIDS." (PMID 28241075, 2017). "We also showed that CXCR4-edited primary CD4+ T cells proliferated normally and were resistant to HIV-1 infection." (PMID 29141633, 2017). "It is only in end-stage HIV-1 infection that characteristic involuted GC are observed, interpreted as “burnt out” follicles, at a time when CD4 T cells in lymph nodes are almost completely depleted." (PMID 28553284, 2017). "In the context of HIV-1 infection, disease severity, reduction of CD4 T-cell counts, and poor immune restoration after ART are associated with sustained and elevated IFN-I expression." (PMID 29301196, 2017). "Excitingly, their study of the NSG mouse transferred with modified primary CD4+ T cells showed a significant survival advantage in the presence of HIV-1 infection in vivo compared to the unmodified group." (PMID 28904745, 2017). "HIV-1 infection is characterized by continuous activation, rapid turnover, and activation-induced cell death of CD4+ and CD8+ T cell populations." (PMID 28125732, 2017). "At the same time, Tfh cells act as the major CD4+ T cells compartment for HIV-1 infection, replication, and long-lived viral reservoirs." (PMID 29163506, 2017). "Numbers and distributions of CD4+ memory and regulatory T cells, macrophages and hematopoietic progenitor cells were significantly altered by HIV-1 infection and by both ART regimens." (PMID 28279181, 2017). "Estimated prevalence of CSF escape in Boston and NNTC cohorts was 6.0% and 6.8%, respectively; median age was 50, duration of HIV-1 infection 17 years, CD4 count 329 cells/mm3 and CD4 nadir 21 cells/mm3." (PMID 28328546, 2017). "In blood, during primary HIV-1 infection, the main population of proliferating CD4+ T cells are highly activated CD38highCCR5+Ki-67+ cells, and include HIV-specific Th1 cells." (PMID 28553284, 2017). "The expression of CD4 and intracellular p24—a measure of HIV-1 infection—was used to delineate 5 different T cell subsets." (PMID 29023371, 2017). "Selective upregulation of miRNA expression was produced by intracellular Tat during HIV-1 infection in CD4+ T cells." (PMID 28968466, 2017). "In our previous study, the two targeting CXCR4 sgRNAs and Cas9 efficiently inhibited HIV-1 infection in CD4+ T cells." (PMID 28904745, 2017). "This would be consistent with low CD4 expression being a major hurdle for efficient HIV-1 infection in differentiated THP-1s." (PMID 29301198, 2017).
HIV-1 infection (continued). "HIV-1 infection of CD4+ T lymphocytes and myeloid cells is characterized by a profound immunodeficiency leading to opportunistic infections and tumor development in most infected individuals in the absence of combination antiretroviral therapy (cART)." (PMID 28211903, 2017). "Nonetheless, the overall pattern of HIV-1 integration site selection is conserved across many different cell lines and primary cells and we detected the selective effect of digoxin on HIV-1 infection in primary memory CD4+ T-cells too." (PMID 28727807, 2017). "Untreated HIV-1 infection leads to a gradual depletion of CD4+ T cells forcing the virus to continuously adapt to an ever-decreasing number of suitable target cells." (PMID 28264054, 2017). "Transcriptome data on HIV-1 infection remains limited to CD4+ T cell lines, mitogen-activated CD4+ T cells and bulk tissue samples from HIV-1-infected individuals." (PMID 28241075, 2017). "The bNAbs or IgG conjugated with CD4 or CD4 domain(s), so-called immunoadhesins, have also displayed substantial in vitro and in vivo efficacies against HIV-1 infection." (PMID 28529952, 2017). "HIV-1 infection of CD4+ T cells leads to their death by apoptosis during productive infection or pyroptosis during abortive infection, and in vivo, there is likely to be a combination of these types of death associated with infection." (PMID 29312342, 2017). "Of note, OX40-OX40L signaling promoted the survival of memory CD4+ T cells within the gut lamina propria, and enhanced productive HIV-1 infection in activated blood CD4+ T cells." (PMID 28241075, 2017). "In most of the situation the acute phase of HIV-1 infection progresses to the latent phase (chronic) accompanied with markedly diminishing CD4+ cell count." (PMID 28273892, 2017). "As CD4+ T cells are more permissive to HIV-1 infection and replication than macrophages and MDDCs, this can probably be explained by the lack of cGAS expression in CD4+ T cells." (PMID 29379496, 2017). "HIV-1 infection of CD4+ T cells involves binding of the viral protein gp120 to the primary cellular receptor CD4 and either of the co-receptors, CCR5 or CXCR4." (PMID 28904745, 2017). "We have previously shown that atorvastatin inhibits activation of CD4+ T cells and ensuing virus replication during HIV-1 infection by restricting the cell cycle and expression of activation markers." (PMID 29228684, 2017). "The effect of different concentrations of MVC in the reactivation of latent NL4.3-wt HIV-1 strain was studied in CD4+ primary T lymphocytes treated with CCL19 or IL-7 before HIV-1 infection." (PMID 28539614, 2017). "IRF-1 expression was then evaluated after de novo HIV-1 infection of primary human CD4+ T cells; an early 2- to 3-fold stimulation of IRF-1 expression, was followed by an inhibition of IRF-1 expression to levels present in uninfected cells." (PMID 27795392, 2016). "We tested the ability of Cas9/gRNAs to suppress HIV-1 infection of CD4+ T-cells prepared from healthy individuals." (PMID 26939770, 2016). "In the search for a cure for HIV-1 infection, histone deacetylase inhibitors (HDACi) are being investigated as activators of latently infected CD4 T cells to promote their targeting by cytotoxic T-lymphocytes (CTL)." (PMID 27529554, 2016). "HIV-1 infection is associated with major structural and immunological disruption of the GI tract due in part to high levels of HIV-1 replication and CD4 T cell depletion that occur in the earliest stages of infection." (PMID 26762145, 2016). "By contrast, the blockage of let-7i with a specific inhibitor resulted in elevated CD4+ T cell apoptosis during HIV-1 infection." (PMID 27145859, 2016). "HIV-1 infection begins with the interaction between viral gp120/gp41 and CD4/co-receptors on host cells and ends with the integration of viral DNA into host genome." (PMID 27473095, 2016).
HIV-1 infection (continued). "We first evaluated the impact of these HAMB species on productive HIV-1 infection levels in LP CD4 T cells in vitro using R5-tropic HIVBaL." (PMID 26762145, 2016). "We investigated if central memory CD4 T cells from patients with HIV-1 infection have a gene expression profile impeding proliferation and survival, despite their activated state." (PMID 27875993, 2016). "Due to the loss of CD4+ T cells in HIV-1 infection, we also found a decreased frequency of CD4+ CD56+ T cells in HIV-1 infection." (PMID 27814766, 2016). "In summary, our study indicates that HIV-1 infection leads to the downregulation of the let-7i/IL-2 axis and contributes to CD4+ T cell death." (PMID 27145859, 2016). "HIV-1 infection of Jurkat cells or primary CD4+ T cells slightly increased the frequency of the RRACH motif within the m6A peaks by 0.2–0.8%, but slightly decreased the GGACU motif frequency by 0.2–0.4%." (PMID 27371828, 2016). "E. coli significantly enhanced HIV-1 infection in LP CD4 T cells as measured by intracellular p24 staining as expected." (PMID 26762145, 2016). "Regulatory T cells (Treg), a specialized subpopulation of CD4+ T cells, are targets for HIV-1 infection." (PMID 26785250, 2016). "HIV-1 infection is characterized by a decline of CD4+ lymphocyte levels and systemic immune hyperactivation." (PMID 27382604, 2016). "Of note, for HIV-1 infection, the characteristics of CD4+ subset and its capacity to mediate ADCC responses were missed in the study due to a very low cells number resulting unreliable results." (PMID 27814766, 2016). "Collectively, these results confirmed that AAT inhibited HIV-1 infection by blocking virus entry into CD4+ T cells." (PMID 27473095, 2016). "After CD4 T cell engraftment and HIV-1 infection, mice were bled at 10-day intervals to assess T cell survival and expansion." (PMID 27855210, 2016). "We have shown here that BmA can potently bind DC-SIGN and block HIV-1 trans-infection of CD4+ enriched T-cells and thereby potentially play a role in modulating HIV-1 infection or replication in exposed or infected individuals, respectively." (PMID 26808476, 2016). "Normally, HIV-1 infection begins with the interaction between gp120/gp41 and CD4/co-receptors, which is then followed by viral core entry, RNA reverse transcription and DNA integration into the host genome." (PMID 27473095, 2016). "Overall, both coinfected and HIV-1-monoinfected patients responded well to the Truvada-based cART, with HIV-1 infection markers CD4+ T-cell counts and HIV-1 viral load showing positive response." (PMID 27800524, 2016). "Here, we show that YTHDF1–3 proteins recognize m6A-modified HIV-1 RNA and inhibit HIV-1 infection in cell lines and primary CD4+ T-cells." (PMID 27371828, 2016). "However, it is still debating whether TRAIL-mediated apoptosis contributes to CD4+ T cell depletion, the hallmark of HIV disease progression, although HIV-1 infection upregulates in vivo DR5 expression on CD4+ T cells, which are then prone to TRAIL-mediated apoptosis." (PMID 26871575, 2016). "Following seroconversion after HIV-1 infection, females have 40% less viral load and more cluster of differentiation 4 (CD4)+ cells than males, but at the same level of viremia, disease severity and progression to acquired immune disease are faster in women." (PMID 29083382, 2016). "gC1qR, as an inhibitor of HIV-1 infection, can block the interaction between CD4 and gp120 and prevent viral entry." (PMID 28066413, 2016). "It is well known that activated CD4+ T cells are highly permissive to HIV-1 infection, whereas resting CD4+ T lymphocytes are refractory to HIV-1 infection." (PMID 27922067, 2016). "Regardless of taxonomic grouping and the relative levels of abundance in vivo, HAMB species enhanced HIV-1 infection in LP CD4 T cells." (PMID 26762145, 2016). "The silencing of IL-2 by siRNA diminished the let-7i-mediated resistance of CD4+ T cells to HIV-1 infection-induced apoptosis." (PMID 27145859, 2016).
HIV-1 infection (continued). "We found that overexpression of YTHDF proteins in target cells significantly inhibited HIV-1 infection, while knockdown of these proteins in primary CD4+ T-cells enhanced HIV-1 infection." (PMID 27371828, 2016). "First, in order to analyze HIV-1 infection under HSP conditions, we infected CD4+ T cells with two minimal lentiviral vectors encoding a GFP marker gene under the control of either the HIV-1 LTR (Lenti LTR-GFP) or the EF-1α promoter (Lenti EF-GFP)." (PMID 27990142, 2016). "Further, we found that lentivirally-delivered CRISPR/Cas9 reduces viral replication upon HIV-1 infection of primary cultured CD4+ T-cells." (PMID 26939770, 2016). "The objective of this paper is to correlate the MRI distribution of cryptococcal meningoencephalitis in HIV-1 infection patients with CD4 T cell count and immune reconstitution effect." (PMID 26871791, 2016). "We provide the first evidence in two physiologically relevant HIV-1 infection models that shows CCR5 interaction with a dual-tropic HIV-1 Env plays a significant role in Env-induced depletion of bystander CD4 T cells." (PMID 27026376, 2016). "We infected primary human CD4+ T cells with HIV-1NL4-3 virus and found that, along with the infection, the levels of mature let-7i miRNA in CD4+ T cells decreased gradually, which is in agreement with the IL-2 expression change during HIV-1 infection." (PMID 27145859, 2016). "This is the first study to comprehensively study the Tfh subset of CD4+ T cells and the IgA+ B cell subset in human gut biopsies during HIV-1 infection." (PMID 27822211, 2016). "The persistent HIV-1 reservoir that is maintained predominantly in CD4+ T cells in persons on cART is the major barrier to curing HIV-1 infection." (PMID 27247230, 2016). "In this study, the milk exosomes bound to monocyte-derived dendritic cells (MDDCs) and inhibited HIV-1 infection of MDDCs and the subsequent viral transfer to CD4+ T cells." (PMID 26981123, 2016). "We and others have demonstrated that CD4+ T cells and macrophages from HIC are less susceptible to HIV-1 infection than cells from other patients." (PMID 27505169, 2016). "Many factors contribute to the depletion of CD4+ T cells in HIV-1 infection, including viral cytotoxic factors, host anti-infection immune response and aberrant immune activation, which adds to normal immune defense mechanisms." (PMID 27145859, 2016). "We went to some length to establish the assay in CD4+ T cells because of their relevance for HIV-1 infection." (PMID 27107820, 2016). "The role of CD4+ T memory cells (including memory stem cells) is well known during all stages of HIV-1 infection." (PMID 26996968, 2016). "When compared to CD4-depleted exosomes from CD4+ T cells, CD4-containing exosomes efficiently inhibited HIV-1 infection." (PMID 26981123, 2016). "CD4+ T cells are the first productively infected cell type detected in primary HIV-1 infection and TF HIV-1 strains, which establish de novo clinical infection, are less sensitive to inhibition by type I interferon (IFN) than chronic controls are." (PMID 27531907, 2016). "In vitro and in humanized mice, primary CD4 T cells were protected and expanded following HIV-1 infection." (PMID 27855210, 2016). "PH1N1 infection increased CD4 expression in the plasma membrane of HIV-1-infected Jurkat cells compared with HIV-1 infection alone." (PMID 26848681, 2016). "We observed the expected elevation of CD4+ T cell apoptosis concomitant with HIV-1 infection, which is consistent with the decreased IL-2 level." (PMID 27145859, 2016). "Previous data have shown increased levels of soluble MIC A during HIV-1 infection as well as reduced levels of MIC A on the surface of CD4 T cells in HIV-1 infected patients possibly due to MIC A/B shedding by HIV-1 infected cells." (PMID 27529554, 2016). "Because myeloid cells and CD4+ T cells from human peripheral blood are the primary target cells during HIV-1 infection, to this end, we examined SAMHD1 expression in these cells." (PMID 27922067, 2016).